MLF1 (myeloid leukemia factor 1)
Description:
Involved in lineage commitment of primary hemopoietic progenitors by restricting erythroid formation and enhancing myeloid formation. Interferes with erythropoietin-induced erythroid terminal differentiation by preventing cells from exiting the cell cycle through suppression of CDKN1B/p27Kip1 levels. Binds DNA and affects the expression of a number of genes so may function as a transcription factor in the nucleus.
Tractability: Small molecule: a structure with a bound ligand is known. Antibody: the Human Protein Atlas places it where antibodies can reach. PROTAC: ubiquitination databases record sites on it.
Gene: Protein-coding gene on chromosome 3 (158,571,163 to 158,607,252, forward strand). Ensembl gene ENSG00000178053.
Subcellular location: Cytoplasm; Nucleus; Cell projection, cilium; Cytoplasm, cytoskeleton, cilium basal body
Subcellular location (Human Protein Atlas): Basal body; Centrosome; End piece; Mid piece; Nucleoplasm; Principal piece; Cytosol; Focal adhesion sites; Plasma membrane; Vesicles
Gene Ontology:
Molecular function: protein binding; protein domain specific binding; DNA binding
Biological process: regulation of cell cycle G1/S phase transition; DNA-templated transcription; myeloid progenitor cell differentiation; regulation of DNA-templated transcription
Cellular component: nucleus; perinuclear region of cytoplasm; ciliary basal body; cilium; cytoplasm
Genetic constraint (gnomAD): Loss-of-function variants: 18 observed, 21.21 expected, observed/expected ratio (o/e) 0.85, 90% interval 0.59 to 1.26. The upper end of that interval is the gene's LOEUF score, 1.26, which puts it in group 5 of 6, group 1 being the genes least tolerant of losing a copy. Missense variants: 203 observed, 223.86 expected, observed/expected ratio (o/e) 0.91, 90% interval 0.81 to 1.02. Synonymous variants: 57 observed, 71.54 expected, observed/expected ratio (o/e) 0.8, 90% interval 0.64 to 0.99.
Homologues: Orthologues: chimpanzee MLF1 (94% identical), macaque MLF1 (89% identical), rabbit MLF1 (81% identical), guinea pig MLF1 (78% identical), pig MLF1 (78% identical), rat Mlf1 (78% identical), mouse Mlf1 (76% identical), dog MLF1 (71% identical), tropical clawed frog mlf1 (50% identical), zebrafish mlf1 (42% identical), Drosophila melanogaster Mlf (30% identical), Caenorhabditis elegans Y17G7B.17 (24% identical). Paralogues in human: MLF2 (35% identical).